ANXA2 (annexin A2)
Diseases named in the same sentence as ANXA2 in open-access papers (continued):
Sharing a sentence is not in itself a finding about the gene and the disease.
ovarian carcinoma (50 papers, 2011 to 2026). A malignant neoplasm originating from the surface ovarian epithelium. "CAR(2448) recognises an N-linked glycoepitope of ANXA2 that is expressed by ovarian cancer cell lines with an epithelial EMT phenotype." (PMID 31936170, 2020). "The histological results confirmed the association of HE4 and ANXA2 expression with the degree of malignancy of ovarian cancer." (PMID 25362534, 2014). "Our findings suggest that the extracellular form of annexin A2 found in the cancer associated stroma in the ovarian cancer tissues may represent a cleaved secreted form of annexin A2, which may assist ovarian cancer progression and metastasis." (PMID 23945256, 2013). "CA125, in combination with annexin A2 (ANXA2), showed 100% sensitivity and improved accuracy in distinguishing stage IA ovarian cancer from benign tumors." (PMID 38275400, 2024). "The interaction between ANXA2 and its binding proteins plays a significant role in the tumor microenvironment by promoting cancer metastasis in ovarian cancer." (PMID 37185759, 2023). "Our findings show that ANXA2 was suppressed in the 9-methoxycanthine-6-one-treated A2780 ovarian cancer cell line." (PMID 35163852, 2022). "Based on IPA analysis, 5 proteins, namely PKM, ANXA2, LGAL3, HNRNP1A1, PRDX3 and GAPDH, were found to be associated with the apoptosis signaling pathway in A2780 ovarian cancer cell line." (PMID 35163852, 2022). "In recent years, proteomic studies also documented that ANXA2 was regarded as an important functional protein in exosomes secreted by bladder, colorectal and ovarian cancer cells." (PMID 34725902, 2021). "Our previous study has demonstrated that HE4 is highly expressed in ovarian cancer tissues, and that the interaction between HE4 and annexin A2 promotes the invasion and metastasis of ovarian cancer." (PMID 34107979, 2021). "Alternatively, a novel RNA nanoparticle harboring an AnxA2 aptamer was developed to target ovarian cancer for doxorubicin delivery." (PMID 33810523, 2021). "In conclusion, to the best of our knowledge, we demonstrated for the first time that the expression of ANXA2 in exosomes derived from ovarian cancer cells varies with the content of ANXA2 in these cells." (PMID 34725902, 2021). "The expression of ANXA2 in ovarian cancer cells was significantly higher than that in HMrSV5 cells (p < 0.05)." (PMID 34725902, 2021). "Ultracentrifugation was further utilized to extract exosomes derived from ovarian cancer cells with up‐ or downregulated ANXA2 expression." (PMID 34725902, 2021). "In this study, we focused on the effect and potential mechanism of exosomal ANXA2 derived from ovarian cancer cells on peritoneal implantation and metastasis of tumours." (PMID 34725902, 2021). "Our previous research has confirmed that ANXA2 was significantly associated with FIGO stages, pathological grade, lymph node metastasis and poor prognosis of ovarian cancer." (PMID 34725902, 2021). "The influence of exosomal ANXA2 on biological characteristics of HMrSV5 cells was further detected through co‐cultured with exosomes derived from ovarian cancer cells with downregulated or upregulated ANXA2 protein." (PMID 34725902, 2021). "What is more, overexpression of ANXA2 promoted the invasion and metastasis of ovarian cancer cells and the tumorigenesis ability of transplanted tumours in nude mice." (PMID 34725902, 2021). "OVCAR3 and ES‐2 ovarian cancer cells were further chosen to construct stable high and low expression of ANXA2 by lentiviral transfection." (PMID 34725902, 2021). "IGROV-1 and SKOV3 are ovarian cancer cell lines which have high expression of ANXA2, corresponding to highly antigen positive, and partially antigen positive ovarian malignancy populations." (PMID 31936170, 2020). "In summary, CAR(2448) targets a glycosylated epitope of ANXA2, which was previously shown to be expressed across various epithelial ovarian cancer cell lines." (PMID 31936170, 2020).
ovarian carcinoma (continued). "CAR(2448) induces specific anti-tumour functions upon recognition of target ovarian cancer cells expressing ANXA2 in vitro, inducing inflammatory cytokine secretion and potent cytotoxicity against target cells." (PMID 31936170, 2020). "Both PRDX1 and ANXA2 are elevated in stage I endometrial cancer, and ANXA2 has been suggested as a potential biomarker for recurrent endometrial cancer and in ovarian cancer progression (regulation of β-catenin-driven epithelial-mesenchymal transition)." (PMID 32106990, 2020). "We confirmed that ANXA2 was highly expressed in ovarian cancer, especially serous and mucinous cystadenocarcinoma, and that its high expression was closely associated with lymph node metastasis." (PMID 31474227, 2019). "Annexin A2 was identified by mass spectrometry to be up-regulated by ovarian cancer-peritoneal cell interactions." (PMID 30621740, 2019). "The interaction between human epididymis protein 4 (HE4) and annexin A2 (Annexin A2) has been found in ovarian cancer." (PMID 31210752, 2019). "Annexin A2 is increased in serous ovarian cancer and plays an essential role in ovarian cancer invasion and metastasis." (PMID 30621740, 2019). "Both the Oncomine and GEPIA database analyses showed that ANXA2 mRNA expression level was significantly upregulated in ovarian cancer." (PMID 31474227, 2019). "Our previous studies reported that annexin A2 plays an important role in ovarian cancer invasion and metastasis and increased expression of both annexin A2 and S100A10 is associated with poor serous ovarian cancer outcome." (PMID 30621740, 2019). "ANXA2/3/8/11 mRNA expression levels were significantly upregulated in ovarian cancer, and ANXA5/6/7 mRNA expression levels were significantly downregulated." (PMID 31474227, 2019). "Research finds that ANXA2 abnormal expression in cervical cancer, ovarian cancer, choriocarcinoma and other gynecological malignancies and AM also has biological behavior similar to a malignant tumor." (PMID 31183557, 2019). "ANXA2 is a HE4-interacting protein in ovarian cancer which was discovered by our research group through mass spectrum analysis in the preliminary phase." (PMID 31210752, 2019). "Although many studies have investigated the functional role of annexin A2 in cancer cells, including ovarian cancer, S100A10 has been less studied." (PMID 30572596, 2018). "We recently demonstrated that high stromal annexin A2 and high cytoplasmic S100A10 expression is associated with a 3.4-fold increased risk of progression and 7.9-fold risk of death in ovarian cancer patients." (PMID 30572596, 2018). "C Ricciardelli’s team used an anti-ANXA2 antibody to reduce both tumor growth and metastasis in an ovarian cancer mice model (SK-OV3)." (PMID 29598816, 2018). "For example, an anti-ANXA2 mAb reduced ovarian cancer cell invasion using a chick chorioallantoic membrane assay." (PMID 29568351, 2018). "In support of these findings, ANXA2 siRNA or neutralizing antibodies significantly inhibit motility and invasion of ovarian cancer cells in vitro and in vivo." (PMID 27402115, 2016). "In the preliminary study, a known protein annexin a2 was discovered as a binding partner of HE4 by mass spectrometry in ovarian cancer cells." (PMID 26362938, 2015). "The ANXA2 was detected in all cases of stage III to IV ovarian cancer at a higher rate, compared to stages I to II (65.63%)." (PMID 25362534, 2014). "Further studies are necessary to investigate the role of S100A4 in the interaction between HE4 and ANXA2 in ovarian cancer cells." (PMID 25362534, 2014). "ANXA2 was shown to promote the invasion and metastasis of ovarian cancer cells through the activation of MMP2." (PMID 25362534, 2014). "HE4 and ANXA2 interaction was then validated in three ovarian cancer cell lines, which suggested that such an interaction is present in ovarian cancer tissues." (PMID 25362534, 2014).
ovarian carcinoma (continued). "Increased levels of annexin A2 were also present in ovarian cancer cells located adjacent to the peritoneal cells in the omental implants tissues." (PMID 23945256, 2013). "The functional role of annexin A2 in ovarian cancer cell motility and invasion was also assessed using annexin A2 neutralizing antibody." (PMID 23945256, 2013). "The in vivo findings from our CAM model and intraperitoneal xenograft mouse model were consistent with our in vitro observations demonstrating annexin A2 promotes ovarian cancer cell motility, invasion and tumor growth." (PMID 23945256, 2013). "Annexin A2 siRNAs were used to evaluate the effects of annexin A2 suppression on ovarian cancer cell adhesion, motility, and invasion." (PMID 23945256, 2013). "We observed a shift in the full length 37 kDa annexin A2 band to a 35 kDa isoform in the CM of co-cultured ovarian cancer and peritoneal cells." (PMID 23945256, 2013). "One of the proteins identified by 2D gel electrophoresis and mass spectrometry to be regulated by ovarian cancer-peritoneal cell interactions was annexin A2." (PMID 23945256, 2013). "Anti-annexin A2 antibodies significantly blocked ovarian cancer cell invasion in the CAM model and cancer cell peritoneal dissemination in the intraperitoneal xenograft mouse model." (PMID 23945256, 2013). "We utilized an intraperitoneal xenograft mouse model to assess the role of annexin A2 in ovarian cancer metastasis in vivo." (PMID 23945256, 2013). "In conclusion, our findings demonstrate that annexin A2 plays an important role in ovarian cancer metastasis." (PMID 23945256, 2013). "This study investigated annexin A2 expression in serous ovarian cancer tissues and cell lines and performed functional in vitro and in vivo studies to examine its role in ovarian cancer cell adhesion, motility, invasion and metastasis." (PMID 23945256, 2013). "Annexin A2 plays a critical role in ovarian cancer metastasis and is therefore a potential novel therapeutic target against ovarian cancer." (PMID 23945256, 2013). "Our recent research identified the protein annexin A2 to be regulated by ovarian cancer-peritoneal cell interactions." (PMID 23945256, 2013). "In this study, annexin A2 was regulated as a result of ovarian cancer and peritoneal cell interactions." (PMID 23945256, 2013). "Strong annexin A2 expression in stromal cells was observed for all clinical stages of human ovarian cancer (stage I to IV) compared with normal ovaries, serous cystadenomas and borderline ovarian tumors." (PMID 23945256, 2013). "In this study, we have demonstrated that suppression of annexin A2 using siRNA decreased ovarian cancer cell adhesion to the peritoneal cells, cell motility, and invasion in vitro." (PMID 23945256, 2013). "Annexin A2 expression was examined by qRT-PCR and western blotting in ovarian cancer cell lines and immunohistochemistry in serous ovarian carcinoma tissues." (PMID 23945256, 2013). "Collectively these results provide strong evidence that annexin A2 plays a pivotal role in ovarian cancer progression and metastasis." (PMID 23945256, 2013). "Our immunohistochemical studies showed annexin A2 expression in both the membrane and cytoplasm of ovarian cancer cells, but high annexin A2 levels were also observed in the cancer associated stroma." (PMID 23945256, 2013). "This study investigated the role of annexin A2 in ovarian cancer metastasis and its potential utility as a novel therapeutic target, using in vitro and in vivo ovarian cancer models." (PMID 23945256, 2013). "Strong annexin A2 immunostaining was observed in the peritoneal cells of the omentum and in the peritoneal cells adjacent to ovarian cancer cells in the omentum." (PMID 23945256, 2013). "It has been found that ANXA2 could overexpress in multitumors, including ovarian cancer, breast cancer, and glioma and enhance the expression of plasminase receptor on the surface of tumor cells." (PMID 35211410, 2022).
ovarian carcinoma (continued). "In this study, exosomal annexin A2 (ANXA2) derived from ovarian cancer cells was co‐cultured with human peritoneal mesothelial (HMrSV5) cells; functional experiments were conducted to explore the effects of exosomal ANXA2 on the biological behaviour of HMrSV5 and the related mechanisms." (PMID 34725902, 2021). "Interestingly, stromal ANXA2 staining and cytoplasmic S100A10 immunostaining correlated with increased risk of ovarian cancer progression and death." (PMID 34944416, 2021). "This study showed that ANXA2 in ovarian cancer cells can be transferred to HMrSV5 cells through exosomes, exosomal ANXA2 can not only promote the migration, invasion and apoptosis of HMrSV5 cells, but also regulates morphological changes and fibrosis of HMrSV5 cells." (PMID 34725902, 2021). "HE4/ANXA2 promoted the invasion and migration of ovarian cancer cells." (PMID 31210752, 2019). "Therefore, we believe that ANXA2 and ANXA4 are closely associated with the tumorigenesis and progression of ovarian cancer." (PMID 31474227, 2019). "Furthermore, the current study found that in addition to ovarian cancer, ANXA2 and HE4 also interact in endometrial carcinoma, and co-localized in the cell membrane and cytoplasm." (PMID 26362938, 2015). "ANXA2 expression was detected in the membrane and cytoplasm of ovarian cancer cells." (PMID 25362534, 2014). "Moreover, our study demonstrated annexin A2 plays a role in ovarian cancer cell adhesion to the peritoneal cells." (PMID 23945256, 2013). "We confirmed that plasmin cleaved recombinant annexin A2 and we demonstrated that annexin A2 cleavage in co-cultured ovarian cancer and peritoneal cells could be partially blocked by α2-antiplasmin." (PMID 23945256, 2013). "Annexin A2 is therefore a promising novel therapeutic target against ovarian cancer." (PMID 23945256, 2013). "We investigated whether annexin A2 cleavage in the ovarian cancer peritoneal cell co-culture could be inhibited by specific proteases." (PMID 23945256, 2013). "To determine whether annexin A2 promotes ovarian cancer metastasis, we examined the effects of knocking down annexin A2 expression on ovarian cancer cell adhesion to the peritoneal cells, motility, and invasion." (PMID 23945256, 2013). "However, further studies are required to investigate annexin A2 cleavage mechanisms, the functional role of cleaved annexin A2 and post-translational modifications of annexin A2 in ovarian cancer." (PMID 23945256, 2013). "Annexin A2 was shown to be expressed in human ovarian cancer and peritoneal cell lines." (PMID 23945256, 2013). "Therefore, we speculate that the interaction between CD147 and HE4 may regulate the occurrence, development, invasion and metastasis of ovarian cancer in the form of protein complex, in which ANXA2 may play a "bridge" role." (PMID 35003362, 2021). "However, the function and mechanism of exosomal ANXA2 on invasion, metastasis and abdominal implantation of ovarian cancer remain unclear." (PMID 34725902, 2021). "Moreover, high stromal annexin A2 and high cytoplasmic S100A10 expression in serous ovarian cancer tissues are associated with a 3.4-fold increased risk of progression and a 7.9-fold risk of ovarian cancer death." (PMID 30572596, 2018). "Furthermore, the HE4 and ANXA2 complex may promote the invasion and metastasis of ovarian cancer cells by activating MMPs and promoting ECM remodeling." (PMID 25362534, 2014). "However, the knowledge on the role of annexin A2 in ovarian cancer is very limited." (PMID 23945256, 2013). "However, in metastatic omental implants, a higher proportion of ovarian cancer cells immediately adjacent to the peritoneal cells were annexin A2 positive (8/9) compared to ovarian cancers cells at a greater distance from the peritoneum (4/9) (P = 0.046, Pearson Chi Square)." (PMID 23945256, 2013).
ovarian carcinoma (continued). "A combined panel of annexin A2 (ANXA2) and CA125 showed a sensitivity of 100%, a specificity of 63.6%, and an accuracy of 71.4% for distinguishing stage IA ovarian cancer from benign ovarian lesions, which was more accurate than the CA125 detection alone." (PMID 36233339, 2022). "ANXA2, a gene in the same family as ANXA6, is frequently up-regulated in various tumors, such as ovarian cancer." (PMID 36712880, 2022). "A more recent study evaluated the immunostaining of both ANXA2 and S100A10 in a large cohort of epithelial ovarian cancer tissue samples and found that enhanced expression of both proteins in the stroma was associated with reduced OS." (PMID 34944416, 2021). "ANXA2 knockdown suppressed β-catenin expression and inhibited EMT and invasion in ovarian cancer cells." (PMID 34685653, 2021). "A monoclonal AnxA2 antibody not only allowed monitoring EMT in breast and ovarian cancers, but also provided antibody-dependent cell toxicity and efficient killing when conjugated to cytotoxic drugs and expressed as a chimeric immunoglobulin G1." (PMID 33810523, 2021). "We firstly detected the expression level of ANXA2 in CaoV3, OVCAR3, SKOV3 and ES‐2 ovarian cancer cells and HMrSV5 cells by Western blot." (PMID 34725902, 2021). "We further confirmed the expression of ANXA2 in exosomes derived from OVCAR3 and ES‐2 ovarian cancer cells with Western blot." (PMID 34725902, 2021). "Previous studies have found that the interaction between ANXA2 and HE4 promotes the invasion and migration of ovarian cancer cells by activating MAPK and FOCAL signaling pathways 16,20." (PMID 35003362, 2021). "We further added the exosome inhibitor GW4869 to the culture medium of ovarian cancer cells (OVCAR3+GW4869 and ES‐2+GW4869) to explore its effect on the expression of ANXA2 and biological behaviours of HMrSV5 cells." (PMID 34725902, 2021). "Here, we describe the development of an anti-annexin A2 CAR, CAR(2448), derived from an antibody found to have activity against epithelial ovarian cancer cell lines." (PMID 31936170, 2020). "Both databases showed that ANXA2, ANXA3, ANXA8, and ANXA11 mRNA expression levels were upregulated in ovarian cancer compared with normal tissues, while ANXA5,ANXA6, and ANXA7 mRNA expression levels were downregulated." (PMID 31474227, 2019). "Recent studies have shown that ANXA2 is highly expressed in ovarian cancer and that ANXA3 and ANXA4 are involved in cisplatin resistance in ovarian cancer." (PMID 31474227, 2019). "The results suggested that ANXA2 and ANXA4 were correlated with ovarian cancer tumorigenesis and progression." (PMID 31474227, 2019). "Combining the results of three databases, ANXA2 and ANXA8 mRNA expression levels were upregulated in ovarian cancer and the expression levels increased significantly with advanced FIGO stages." (PMID 31474227, 2019). "The expression of ANXA2 and HE4 were up-regulated simultaneously and their overexpression promoted the malignant behavior of ovarian cancer." (PMID 26362938, 2015). "What’s more, ANXA2 and HE4 interacted in ovarian cancer and promoted the malignant biological behavior." (PMID 26362938, 2015). "Firstly, OVCAR-3, ES-2 and CaoV-3 ovarian cancer cells lysates were precipitated with antibodies specific to HE4 and ANXA2, and the structures of ANXA2 and HE4 in ovarian cancer cells were examined." (PMID 25362534, 2014). "Similarly, the MAP-defined antigens ABCF3 and ANXA2 were also highly expressed across healthy tissues, while CRABP2, although significantly over-expressed in ovarian cancer samples, was expressed at similar or greater levels in several healthy sites." (PMID 36943460, 2023). "We previously showed that CD147 and HE4 were both highly expressed in ovarian cancer tissues 11, and HE4 could interact with ANXA2 to promote malignant biological behavior and EMT process of ovarian cancer 16,20-21." (PMID 35003362, 2021).